ENSG00000274944 (novel protein)
Gene: Protein-coding gene on chromosome 1 (38,864,501 to 38,881,617, reverse strand). Ensembl gene ENSG00000274944.
Genetic constraint (gnomAD): Loss-of-function variants: 4 observed, 10.79 expected, observed/expected ratio (o/e) 0.37, 90% interval 0.18 to 0.85. Missense variants: 87 observed, 94.47 expected, observed/expected ratio (o/e) 0.92, 90% interval 0.77 to 1.1. Synonymous variants: 28 observed, 32.89 expected, observed/expected ratio (o/e) 0.85, 90% interval 0.63 to 1.17.